ENSG00000302165 (novel transcript)
Gene: Long non-coding RNA gene on chromosome 6 (52,136,998 to 52,149,708, forward strand). Ensembl gene ENSG00000302165.
Gene Ontology:
Biological process: miRNA-mediated post-transcriptional gene silencing
Cellular component: RISC complex